FBLN5 (fibulin 5)
Diseases named in the same sentence as FBLN5 in open-access papers (continued):
Sharing a sentence is not in itself a finding about the gene and the disease.
COVID-19 (4 papers, 2020 to 2024). A disease caused by infection with severe acute respiratory syndrome coronavirus 2. "Patients with severe/critical COVID-19 symptoms are at a higher risk of extracorporeal coagulation during hemodialysis, which is associated with the upregulation of the vWF/FBLN5 signaling pathway." (PMID 38649864, 2024). "Therefore, we suggest that COVID-19-induced thrombosis is associated with FBLN5." (PMID 38649864, 2024). "In CKD patients, COVID-19 may exacerbate the vascular injury and induce a hypercoagulable state by upregulating vWF/FBLN-5." (PMID 38649864, 2024). "In conclusion, COVID-19 may upregulate the vWF/FBLN5 signaling pathway in the patients with severe/critical symptoms, thereby increasing the likelihood of extracorporeal coagulation during hemodialysis in CKD patients." (PMID 38649864, 2024). "Collectively, these results suggest that the vWF/FBLN5 pathway may play a pivotal role in the regulation of COVID-19-induced extracorporeal coagulation." (PMID 38649864, 2024). "Additionally, the cellular adhesion regulators: calpain small subunit 1 (CAPNS1) and fibulin 5 (FBLN5), were both down-regulated six months after COVID-19." (PMID 39183264, 2024). "We further identified strong genetic correlations (|r| > 0.5) between smaller sets of proteins related to COVID-19 severity, and host proteins relevant to viral replication such as between IL-6-induced proteins (SAA1, SAA2, and CD14) and fibulin 5 (FBLN5)." (PMID 33328453, 2020).
diabetes (4 papers, 2017 to 2025). "Others have reported upregulation of Fbln5 in patients with diabetes, hypertriglyceridemia and a strong family history of CVD." (PMID 33042024, 2020). "In our study, Fbln5 was upregulated in both diabetes and HF diet exposed offspring hearts." (PMID 33042024, 2020). "Thus, the interactions between Fbln5 and pancreatic β-cell functions, which are still poorly understood, may represent novel molecular mechanisms involved in glucose metabolism and provide new insights for the treatment in diabetes." (PMID 28539593, 2017).
pancreatic ductal adenocarcinoma (4 papers, 2018 to 2026). An infiltrating adenocarcinoma that arises from the epithelial cells of the pancreas. "In pancreatic ductal adenocarcinoma, hypoxia upregulates fibulin-5 (FBLN5) expression via TGF-β and phosphoinositide 3-kinase (PI3K)/protein kinase B (AKT) signaling." (PMID 35884382, 2022). "Hypoxic induction of FBLN5 in CAFs isolated from mouse pancreatic ductal adenocarcinoma were reversed by pharmacologic inhibition of TGF-β or PI3K/AKT." (PMID 35884382, 2022). "In pancreatic ductal adenocarcinoma, fibulin-5 is produced by stromal cells, and its expression is induced by TGF-β via PI3K/AKT signaling pathway, serving as a protumorigenic factor." (PMID 30227601, 2018). "In pancreatic ductal adenocarcinoma, fibulin-5 promotes tumor progression by blocking reactive oxygen species production through competing with fibronectin for integrin binding sites, resulting in increased angiogenesis and tumor growth." (PMID 30227601, 2018). "Similarly, in pancreatic ductal adenocarcinoma, an increased expression of fibulin-5 was reported to be induced by TGF-β via the PI3K/AKT signaling pathway." (PMID 34063320, 2021).
bladder cancer (3 papers, 2014 to 2019). "Transfection of FBLN5 in a bladder cancer cell line resulted in decreased growth rates, cell invasion and cell migration compared with non-transfected and empty vector-transfected controls." (PMID 29581841, 2018).
Charcot-Marie-Tooth disease (3 papers, 2017 to 2025). An inherited degenerative disorder involving the peripheral nerves. "FBLN5 mutations are associated with three distinct human diseases, including age-related macular degeneration, cutis laxa, and Charcot-Marie-Tooth disease (CMT)." (PMID 28332470, 2017). "Rare forms of autosomal-dominant Charcot-Marie-Tooth disease (AD-CMT) may be associated with mutations in Fibulin-5 (FBLN5) as AD-CMT is genetically heterogeneous." (PMID 28332470, 2017).
glaucoma (3 papers, 2012 to 2023). Increased pressure in the eyeball due to obstruction of the outflow of aqueous humor. "Lysyl oxidase-like 1, which is linked to Pseudoexfoliation (PEX) glaucoma, and which is heavily bound to the PEX material of PEX patients was very downregulated in Q368X, while other two PEX relevant components, FBN1 and Fibulin 5 (FBLN5), were slightly altered in all four mutants." (PMID 22615763, 2012). "In contrast to the invariance of LOXL1, Fibulin-5 expression in the XFS-TFs was 7.0-fold (p = 0.02) and 10.8-fold +/- 1.0 (p = 0.03) higher than in the POAG or young no glaucoma controls, respectively." (PMID 27391778, 2016).
intrahepatic cholangiocarcinoma (3 papers, 2022 to 2025). A carcinoma that arises from the intrahepatic bile duct epithelium in any site of the intrahepatic biliary tree. "In addition, it was confirmed that LOXL1, the protein interacting with FBLN5, stimulated angiogenesis through the LOXL1-FBLN5/avb3 integrin/FAK-MAPK axis in intrahepatic cholangiocarcinoma, which resulted in favorable conditions for cancer cell metastasis." (PMID 36672502, 2023). "LOXL1 highly expressed in intrahepatic cholangiocarcinoma (ICC) can interact with FBLN5, an extracellular matrix glycoprotein containing the Arg-Gly-Asp (RGD) structural domain." (PMID 36293126, 2022). "In intrahepatic cholangiocarcinoma (ICC), elevated LOXL1 expression interacts with fibulin-5 (FBLN5), an extracellular matrix glycoprotein containing the Arg-Gly-Asp (RGD) motif." (PMID 40786111, 2025).
ischemic stroke (3 papers, 2022 to 2024). A stroke disorder caused by obstruction of blood flow to the brain, due to thrombotic (local blood clot formation) or embolic (due to a blood clot or other material traveling from another site) event. "Taken together, the experimental studies have shown that FBLN5 is neuroprotective for ischemic stroke, whereas clinical studies have found that higher plasma FBLN5 levels in an acute phase are associated with more severe ischemic or hemorrhagic strokes with worse outcomes." (PMID 36499510, 2022). "Hypoxic stress, in ischemic stroke, and relative ischemia, in hemorrhagic stroke, induce fibulin-5 expression in endothelial cells via the hypoxia-inducible factor-1, which is an adaptive response to hypoxic conditions." (PMID 36699006, 2022). "Fibulin-5 is considered a neuroprotective factor that improves neurological prognosis by increasing the blood-brain barrier permeability as a compensatory mechanism after ischemic stroke." (PMID 36699006, 2022).
leiomyoma (3 papers, 2007 to 2021). A well-circumscribed benign smooth muscle neoplasm characterized by the presence of spindle cells with cigar-shaped nuclei, interlacing fascicles, and a whorled pattern. "Moreover, leiomyomas had low expression of FBLN5, which validated as a direct target of miR-200c through interaction with its 3’UTR." (PMID 33460398, 2021). "In contrast, the expression of EGR3, ECM2, THBS1, GAS1 and FBLN5 in scars and RUNX3 and COL18 expression in peritoneal adhesions was higher as compared to leiomyomas." (PMID 17718906, 2007). "We validated the expression of ECM-2, ESM1, THBS1, FBLN5 and COL18A1 in keloids, incisional scars and adhesions and the analysis indicated an elevated expression of ECM2, THBS1 and FBLN5 in keloid/incisional scars and COL18 in peritoneal adhesions as compared to leiomyomas." (PMID 17718906, 2007).
aneurysm (2 papers, 2012 to 2022). Bulging or ballooning in an area of an artery secondary to arterial wall weakening. "The proteins identified in the aneurysm wall include the structural fibulin-5 involved in elastin assembly, the anti-aggregatory and vasodilatory PGI2-producing enzyme prostacyclin synthase, and the water channel aquaporin-1 (AQP1)." (PMID 35203568, 2022).
Aortic dissection (2 papers, 2020 to 2021). Aortic dissection refers to a tear in the intimal layer of the aorta causing a separation between the intima and the medial layers of the aorta. "Lowered fibulin-5 mRNA levels have been linked to patients with aortic dissection: decreased fibulin-5 may contribute to the pathogenesis of aortic dissection by impairing elastic fiber assembly." (PMID 35053160, 2021).
autosomal dominant cutis laxa (2 papers, 2024 to 2025). Autosomal dominant cutis laxa (ADCL) is a connective tissue disorder characterized by wrinkled, redundant and sagging inelastic skin associated in some cases with internal organ involvement. "Autosomal Dominant Cutis Laxa is caused by a mutation in the ELN, FBLN5, or ALDH18A1 genes." (PMID 39480826, 2024).
autosomal recessive cutis laxa type 1A (2 papers, 2021 to 2025). "The two cases presented here, autosomal recessive cutis laxa type 1A caused by a novel FBLN5 variant and ataxia telangiectasia associated with a pathogenic ATM variant, illustrate the diagnostic difficulties related to overlapping clinical features." (PMID 41300699, 2025). "The first involves a child with autosomal recessive cutis laxa type 1A due to a novel pathogenic FBLN5 variant, presenting with pulmonary fibrosis, immunodeficiency, and connective tissue manifestations." (PMID 41300699, 2025). "According to ACMG/AMP criteria, the FBLN5 variant was classified as pathogenic, consistent with autosomal recessive cutis laxa type 1A, while the TNFRSF13B variant was considered a secondary finding of uncertain clinical significance." (PMID 41300699, 2025). "The first was diagnosed with autosomal recessive cutis laxa type 1A (ARCL1A) attributable to a homozygous FBLN5 variant, whereas the second was confirmed with ataxia–telangiectasia (A–T) resulting from a heterozygous ATM frameshift mutation." (PMID 41300699, 2025). "Similarly, patients with homozygous loss-of-function mutations in FBLN5, the gene coding for fibulin-5, develop autosomal recessive Cutis Laxa type IA (ARCL1A)." (PMID 33514025, 2021). "Autosomal recessive cutis laxa type 1A results from mutations in FBLN5, encoding fibulin-5, a protein critical for elastic fiber assembly." (PMID 41300699, 2025).
cardiomyopathy (2 papers, 2015 to 2020). A disease of the heart muscle or myocardium proper. "Beyond pathway analyses, these findings identify Car1, Frzb, and Fbln5 as potential candidates in the pathogenesis of neonatal cardiomyopathy and programming of adult CVD in offspring born to diabetic mothers." (PMID 33042024, 2020).
carotid atherosclerosis (2 papers, 2022 to 2024). A thickening and loss of elasticity of the walls of carotid arteries that occur with formation of atherosclerotic plaques. "We identified possible up-regulated microRNAs associated with FBLN5 after confirming that FBLN5 expression is reduced in unstable samples of carotid atherosclerosis." (PMID 35356421, 2022). "It was discovered that FBLN5 may play an important role in carotid atherosclerosis via has-mir-128 and has-mir-532-3p." (PMID 38694921, 2024). "Our results demonstrate that in patients with carotid atherosclerosis, the expression levels of FBLN5 and anchoring protein in both smooth muscle cells and endothelial cells are reduced, resulting in weak intercellular interactions and increased cell proliferation and migration." (PMID 35356421, 2022). "These miRNAs were up-regulated in a PCR verification experiment, indicating that they may regulate FBLN5 in carotid atherosclerosis." (PMID 35356421, 2022). "In conclusion, FBLN5 may play a role in the progression of carotid atherosclerosis via negative regulatory effects of hsa-miR-128 and hsa-miR-532–3p." (PMID 35356421, 2022). "Therefore, FBLN5 may play an important role in carotid atherosclerosis via hsa-mir-128 and hsa-mir-532–3p as well as become an essential target for treatment." (PMID 35356421, 2022).
Chronic Heart Failure (2 papers, 2014 to 2025). "Similarly, the combination of MAGGIC (Meta-Analysis Global Group in Chronic Heart Failure) score, FBLN5, and FMOD had a significantly larger area under the curve (0.669) than the combination of MAGGIC score+RVD grade (0.572; P=0.02)." (PMID 39823288, 2025).
endometrial cancer (2 papers, 2015 to 2018). Primary or metastatic malignant neoplasm involving the endometrium (mucous membrane that lines the endometrial cavity). "A recent study showed that fibulin-5 is downregulated in human endometrial cancer and that fibulin-5 knockdown in endometrial epithelial cancer cells enhances adhesion and proliferation of cancer cells, indicating its antitumorigenic role in women." (PMID 30227601, 2018).
endothelial dysfunction (2 papers, 2014 to 2020). In vascular diseases, endothelial dysfunction is a systemic pathological state of the endothelium (the inner lining of blood vessels) and can be broadly defined as an imbalance between vasodilating and vasoconstricting substances produced by (or acting on) the endothelium. "FBLN5 encodes a protein that may regulate the production of ROS in the vascular wall and act to protect endothelial dysfunction." (PMID 32194642, 2020).
fibrosarcoma (2 papers, 2019 to 2023). A malignant mesenchymal fibroblastic neoplasm affecting the soft tissue and bone. "The ECM gene cluster including the Lum, Sfrp1, Fbln5, Chad, Kera, Aspn, and Omd genes was found to be distinctly more activated in granulomas than in fibrosarcomas." (PMID 30621584, 2019). "On the contrary, FBLN5 increases DNA synthesis and stimulates motility in fibrosarcoma cells." (PMID 37644092, 2023).
fibrosis (2 papers, 2015 to 2026). the formation of excess fibrous connective tissue in an organ or tissue in a reparative or reactive process. "Patients with FBLN5 levels above this cutoff had a significantly higher prevalence of F3–4 fibrosis stage (81% vs 14%; P < .001) and F4 fibrosis stage (63% vs 10%, P < .001)." (PMID 41362817, 2026). "We further analyzed the value of plasma FBLN5 in predicting advanced fibrosis (F3 or F4) and cirrhosis (F4) using receiver-operating characteristic curves." (PMID 41362817, 2026). "Therefore, the amount of elastic fibers and FBLN5 in the liver provides critical information for assessing both the regression of fibrosis and the clinical course of patients with advanced fibrosis." (PMID 41362817, 2026). "Given the effect of the attenuated inflammatory response in the SnailTg/Fibulin-5 KO on the ECM content of the skin, we tested whether otherbiochemical hallmarks of fibrosis were affected." (PMID 26469761, 2015).
glioma (2 papers, 2020 to 2022). A benign or malignant brain and spinal cord tumor that arises from glial cells (astrocytes, oligodendrocytes, ependymal cells). "FBLN5 is downregulated in stage III and IV glioma and has been shown to inhibit glioma cell proliferation and invasion." (PMID 35198102, 2022).
head and neck cancer (2 papers, 2020 to 2023). A primary or metastatic malignant neoplasm affecting the head and neck.
heart failure (2 papers, 2014 to 2025). Inability of the heart to pump blood at an adequate rate to meet tissue metabolic requirements. "Our study proposes that circulating levels of FMOD and FBLN5 may serve as new biomarkers of RVD in patients with heart failure with reduced ejection fraction." (PMID 39823288, 2025).
hemorrhagic stroke (2 papers, 2022). A stroke caused by a bleed on the brain. "Overexpression of fibulin-5 has been associated with improved clinical outcomes following reperfusion and has been regarded as a biomarker to predict severity and prognosis in both ischemic and hemorrhagic stroke." (PMID 36699006, 2022). "A positive correlation between fibulin-5 levels and functional outcomes measured using the mRS in a 3-month follow-up study in both ischemic and hemorrhagic stroke patients, suggested the ability of fibulin-5 to predict poor prognosis." (PMID 36699006, 2022). "In a clinical setting, plasma FBLN5 levels were reported to increase in an acute phase of both ischemic and hemorrhagic strokes." (PMID 36499510, 2022).
hemorrhoid (2 papers, 2021 to 2023). Dilated veins in the anal canal. "This study will compare the efficacy of Shaobei injection with the rubber band ligation method in the treatment of grade II–III haemorrhoids and investigate its effect on the expression of fibulin-3 and fibulin-5 in the fibulin protein family." (PMID 34797296, 2021). "This is a prospective, randomized, single blind, parallel controlled trial to study the efficacy of Shaobei injection in the treatment of grade II–III hemorrhoids and its effect on the expression of fibulin-3 and fibulin-5 in fibulin protein family." (PMID 34797296, 2021). "In addition, TCM can also increase the level of fibulin-5, restore damaged elastic fibers in hemorrhoid tissues, protect anal cushion tissues, and play a therapeutic role in the treatment of hemorrhoids." (PMID 37927595, 2023).
Hypertension (2 papers, 2020 to 2023). The presence of chronic increased pressure in the systemic arterial system. "Fbln5 (Fibulin 5 or DANCE) was identified as a candidate protein that was expressed differentially in the cerebral arteries compared to two systemic vascular beds at the early-onset of hypertension in the SHR." (PMID 37660920, 2023). "Furthermore, our experimental setup revealed two potential candidate proteins (Fbln5 and Cdh13), whose expressions were critically changed in cerebral arteries compared to systemic arteries at the early-onset of hypertension in the SHR." (PMID 37660920, 2023).
lymph node metastasis (2 papers, 2023 to 2025). "Cox univariate and multivariate analyses showed that the expression levels of FBLN5 and lymph node metastasis rate were independent risk factors related to the prognosis of GC patients." (PMID 36672502, 2023). "Univariate and multivariate analyses showed that FBLN5 expression levels and lymph node metastasis rate were independent risk factors related to GC patient prognosis, which can be combined to construct a nomogram to serve patients." (PMID 36672502, 2023). "In addition, patients with high FBLN5 expression levels were associated with INFc and lymph node metastasis." (PMID 36672502, 2023). "The FBLN5 expression level and lymph node metastasis rate were independent prognostic risk factors for GC patients and could be used to construct a nomogram for assessing patient prognosis." (PMID 36672502, 2023). "Based on the results of the Cox univariate and multivariate analyses, we used the combination of the FBLN5 expression level and lymph node metastasis rate to build a nomogram prediction model for evaluating the prognosis of patients." (PMID 36672502, 2023). "High FBLN5 expression levels were significantly correlated with INFc and N3 lymph node metastasis." (PMID 36672502, 2023). "Moreover, the DCA diagram also clearly showed that the combination of FBLN5 expression and lymph node metastasis rate to assess patient prognosis had better application prospects." (PMID 36672502, 2023). "To further evaluate the relationship between FBLN5 expression levels and patient prognosis, we performed univariate and multivariate Cox analyses and found that FBLN5 expression and lymph node metastasis rates were independently correlated with patient prognosis (p < 0.05)." (PMID 36672502, 2023).
pulmonary fibrosis (2 papers, 2025). Chronic progressive interstitial lung disorder characterized by the replacement of the lung tissue by connective tissue, leading to progressive dyspnea, respiratory failure, or right heart failure. "Previously reported FBLN5-related cases were characterized by lax skin, cardiovascular anomalies, and hernias, while pulmonary fibrosis is rare." (PMID 41300699, 2025).